PTGES3L (prostaglandin E synthase 3 like)
Tractability: No criterion of Open Targets' tractability assessment is met for any kind of drug.
Gene: Protein-coding gene on chromosome 17 (42,968,088 to 42,980,499, reverse strand). Ensembl gene ENSG00000267060.
Gene Ontology:
Molecular function: Hsp90 protein binding
Biological process: chaperone-mediated protein complex assembly
Genetic constraint (gnomAD): Loss-of-function variants: 14 observed, 25.55 expected, observed/expected ratio (o/e) 0.55, 90% interval 0.36 to 0.86. The upper end of that interval is the gene's LOEUF score, 0.86, which puts it in group 3 of 6, group 1 being the genes least tolerant of losing a copy. Missense variants: 187 observed, 193.55 expected, observed/expected ratio (o/e) 0.97, 90% interval 0.86 to 1.09. Synonymous variants: 54 observed, 65.14 expected, observed/expected ratio (o/e) 0.83, 90% interval 0.67 to 1.04.
Homologues: Orthologues: pig PTGES3L (92% identical), mouse Ptges3l (88% identical), guinea pig PTGES3L (87% identical), rat Ptges3l (87% identical), rabbit PTGES3L (71% identical), tropical clawed frog ptges3l (55% identical), zebrafish ptges3l (51% identical), Caenorhabditis elegans daf-41 (21% identical), Drosophila melanogaster p23 (20% identical). Paralogues in human: PTGES3 (42% identical).
Diseases named in the same sentence as PTGES3L in open-access papers:
PTGES3L is named in the same sentence as 3 diseases in open-access papers, as found by Europe PMC text mining. Sharing a sentence is not in itself a finding about the gene and the disease. The quoted sentences say what the papers report.
arthrogryposis (1 paper, 2021). A rare, non-progressive congenital disorder characterized by multiple joint contractures which are present at birth. "Diseases associated with PTGES3L include arthrogryposis, distal, type 2A, and spondylocarpotarsal synostosis syndrome." (PMID 34779768, 2021).
cardiovascular diseases (1 paper, 2022). "Basedon the evidence exemplified above, we could certainly specu­late that the PTGES3L-AARSD1play a promi­nent role in cardiovascular diseases and dysregulation of PTGES3L-AARSD1 wouldbe harmful to human heart." (PMID 37101540, 2022).
PTGES3L also shares sentences with these, for which no sentence is quoted: spondylocarpotarsal synostosis syndrome (1 paper).